ICOS (inducible T cell costimulator)
Diseases named in the same sentence as ICOS in open-access papers (continued):
Sharing a sentence is not in itself a finding about the gene and the disease.
tumor (continued). "In summary, the immunosuppressive effect of ICOS is likely to lead to the survival and escape of tumor cells, affecting the occurrence and development of cancer and the prognosis of patients." (PMID 36855091, 2023). "ICOS expression on the protein level by tumor cells was further validated by immunohistochemical staining." (PMID 37259155, 2023). "While the production of IL-21 and CXCL13 by Tfh cells can stimulate adaptive anti-tumour immunity at a distance, the direct engagement of Tfh cells with B cells through ICOS/ICOSL and CD40L/CD40 binding is also critical to the anti-tumour immune response." (PMID 37936700, 2023). "While broad evidence exists in terms of ICOS expression on the surface of various immune cell subtypes, little is known regarding tumor-intrinsic ICOS protein expression." (PMID 37259155, 2023). "The results of the univariate analysis implied that the factors such as tumor size, regional node involvement, stage, and protein level of ICOS/ICOSL affected the prognosis of patients (p < 0.05)." (PMID 37850501, 2023). "Accordingly, improved antitumor efficacy has been observed with the combination of anti-PD-1 or anti-CTLA-4 in the context of ICOS co-stimulation (i.e., forced ICOSL expression and/or ICOS agonist antibody) in mouse syngeneic tumor models." (PMID 36266600, 2023). "Tumor-associated Tregs highly express immunosuppressive molecules, including FOXP3, CTLA-4, PD-1, CD39, ICOS, CD38, and IL32, as well as several specific surface signaling molecules (PD-L1, PD-L2, interleukin-1 receptor 2, and chemokine CCR8)." (PMID 37187731, 2023). "Tumor growth increased in control, anti–PD-1-, and anti–TIM-3-treated mice, whereas tumor growth was prevented in anti-ICOS–treated mice." (PMID 36480166, 2023). "We identified two loci of interests, referred to as CpG 2 and CpG 4/5, whose methylation strongly correlated with immune infiltration (CpG 2) and differentiation and tumor cell-intrinsic ICOS mRNA expression (CpG 4/5)." (PMID 37259155, 2023). "The inducible T cell co-stimulator (ICOS) is a co-stimulator with the ability to induce tumor immunity by stimulating T cells, including cytotoxic T lymphocytes (CTLs) and Th cells, while promoting immune evasion by stimulating Treg cells." (PMID 36835136, 2023). "Ex vivo treatment of tumor tissue from patients with HNSCC with pembrolizumab significantly increased upregulation of ICOS gene expression relative to untreated controls." (PMID 37593752, 2023). "The high ICOS expression by T cells precludes the study of tumor cell-specific correlation analyses of CpG methylation and mRNA expression in heterogeneous tumors from the TCGA cohort." (PMID 37259155, 2023). "ICOS displays a dualistic in tumors including both anti-tumor effect by promoting T-cell response and enhancing tumor progression." (PMID 38127899, 2023). "Tumor cell-intrinsic ICOS protein and mRNA expression was inducible by pharmacological demethylation with decitabine." (PMID 37259155, 2023). "Accordingly, CpG 4/5 methylation in a heterogeneous tumor represents in part a measure for ICOS mRNA expressing tumor cells." (PMID 37259155, 2023). "Tumor-infiltrating Tregs express high levels of cell surface molecules associated with T-cell activation, such as CTLA4, PD-1, LAG3, TIGIT, ICOS, and TNF receptor superfamily members including 4-1BB, OX40, and GITR." (PMID 37182149, 2023). "In our study, the expression level of ICOS is related to tumor size, regional nodal status, different stages, and recurrence status." (PMID 37850501, 2023). "ICOS/ICOSL signaling has been shown to contribute to anti-tumor immunity through tumor-infiltrating Tr1 cells." (PMID 38127899, 2023). "To date, multiple Phase I and II clinical trials are being conducted for ICOS agonists and ICOS antagonists due to the high expression of ICOS in the tumor microenvironment and duality of function for the treatment of advance solid tumors." (PMID 36774519, 2023).
tumor (continued). "The high expression of ICOS in tumor samples was related to the poor prognosis of UVM and LGG; The positive prognosis was boosted by the strong expression of ICOS in OV, SARC, SKCM, THYM, UCEC, and HNSC." (PMID 36855091, 2023). "In contrast, memory T-cell markers and costimulation makers, including CD27, CD44, CD45RO, ICOS, and 4-1BB, were lower within the tumor core of liver metastases, indicating decreased immune activity, possibly contributing to decreased lymphocyte infiltration." (PMID 37768208, 2023). "There were two exceptions to this observation: the proportion and MFI of ICOS on Vγ4+ cells as well as MFI of JAML on Vγ6+ cells was increased in tumor-bearing KB1P mice." (PMID 36480166, 2023). "A recent study showed that ICOS and PD-1 label tumor-infiltrating T cells for neoantigen recognition in the TME." (PMID 36983005, 2023). "Another study on the immune microenvironment of GC indicated close relationships among the expression of ICOS in Foxp3+ tumor-infiltrating lymphocytes and pDCs, the expression of ICOS-L and TLR9 of pDCs, and H. pylori infection." (PMID 35311157, 2022). "ICOS is a marker of T-cell activation, and it was upregulated in the tumor tissues of obese patients with lung adenocarcinoma (LUAD)." (PMID 35464451, 2022). "Our data demonstrate that ICOS is upregulated on CD4 and CD8 T cells in the peripheral blood and tumor following radiation therapy, and that the combination of a novel ICOS agonist antibody with radiation therapy results in tumor control." (PMID 36056093, 2022). "The use of anti-ICOS antibodies would have conceptual limitations, however, since ICOS is expressed by Tregs and some tumor cells." (PMID 35703176, 2022). "CTLA-4, TIM-3 and ICOS were decreased 6 weeks post-FLOT or CROSS chemoradiotherapy treatment on tumour-infiltrating T cells." (PMID 35366537, 2022). "On the other hand, the expression of ICOS, its association with FOXP3, and its effect on tumour progression are far more complicated." (PMID 35043584, 2022). "C12_CD4, which mainly comprised CD4+ T cells from tumors, was associated with high gene accessibility for markers of tumor-infiltrating regulatory T cells (Tregs), including TNFRSF18, ICOS and CTLA4." (PMID 35668194, 2022). "In humans, Treg increment is related to worse outcomes in many tumor diseases, and the expansion of ICOS-positive Tregs is related to IL-2 therapy unresponsiveness." (PMID 36059465, 2022). "Diphtheria toxin administered to deplete Tregs showed an enhanced tumor rejection in mice with liver metastases and an increase in the expression of IFNγ, ICOS and CD107a on CD8+ T cells." (PMID 36466910, 2022). "More recently, we reported the presence of a subset of CD4 Th cells that co-express PD-1 and ICOS, a phenotype reminiscent of Tfh cells, in the tumor microenvironment (TME) of HNSCC tumors." (PMID 35937775, 2022). "have shown that the expression of glucocorticoid‐induced TNFR (GITR) and ICOS are upregulated in activated tumor‐infiltrating Tregs in patients with primary or metastatic liver cancer." (PMID 35474948, 2022). "The number of ICOS+ Treg cells in tumor and peritumor tissue increased with the progress of tumor stage in patients." (PMID 35311157, 2022). "The ICOS antibody used in this study has agonistic activity resulting in T cell activation and can also mediate Treg reduction in the tumor microenvironment in preclinical models, likely due to antibody-dependent cell-mediated cytotoxicity." (PMID 36056093, 2022). "We therefore sought to investigate the regulation of ICOS expression following tumor radiation and evaluate the potential effects of combining radiation therapy with an ICOS agonist antibody in preclinical mouse tumor models." (PMID 36056093, 2022). "In the tumor microenvironment, ICOS-L is expressed by several types of immune cells, by EC, and often by tumor cells, whereas ICOS is expressed by infiltrating T cells." (PMID 36500861, 2022).
tumor (continued). "We found that we did achieve more statistical significance, for example CTLA-4 and ICOS were significantly decreased on the surface of tumour-infiltrating CD4+ T cells compared with the treatment-naïve setting." (PMID 35366537, 2022). "While ICOS has a dual role in autoimmunity and immunosuppression, it is essential in anti-tumor immune responses." (PMID 35326731, 2022). "ICOS, which is a marker of T cell activation has been shown to play an important role in promoting effector T cell function in anti-tumour immune responses." (PMID 35366537, 2022). "Immune checkpoints such as PDCD1LG2, ICOS, CD28, and CD40 were found to be substantially expressed in the high-risk group, indicating that the tumor microenvironment of the high-risk group had a strong immunosuppressive effect." (PMID 36479092, 2022). "Tregs and ICOS+ Tregs are located mainly in tumor tissue, whereas pDCs are present in peritumoral tissue." (PMID 35619702, 2022). "Intriguingly, ICOS and OPN exert different and often opposite effects upon ICOSL triggering since OPN stimulates, whereas ICOS inhibits, migration of several cell types and tumor angiogenesis." (PMID 36119089, 2022). "Since ICOS is expressed on CD4+ T cells, CD8+ T cells, and NK cells, we aimed to investigate which cell populations are critical for tumor control by radiation therapy and ICOS antibody." (PMID 36056093, 2022). "Here, we report that the coexpression of PD-1 and ICOS (DP CD4+) identified a unique population of CD4+ Th TILs found in the tumor microenvironment (TME)." (PMID 35439168, 2022). "We show that the co-expression of IL1R1 and ICOS uniquely identifies an intratumoural Treg population from all other haematopoietically-derived (CD45+) cells in the tumour or peripheral blood." (PMID 35545675, 2022). "Recent studies reported that tumor-infiltrating CD39+ Tregs in CRC patients expressed different markers such as OX-40, CTLA-4 and ICOS, implicating their high immunosuppressive abilities in inhibiting anti-tumor immune responses." (PMID 35655158, 2022). "Both tumor and peritumor tissue had higher Foxp3+ICOS+/Foxp3+ cell ratio when compared with normal tissue." (PMID 35311157, 2022). "The level of IL-10 increased from normal tissue to tumor tissue, mirroring the distribution of ICOS+ Treg cells." (PMID 35311157, 2022). "The expression of inducible co-stimulator (ICOS) is an important indicator of the anti-tumor response of Th1 cells, and serves as a new potential biomarker for T cell-mediated immunotherapy response." (PMID 36119047, 2022). "Concurrent ICOS pathway engagement further suppressed tumor growth, established a more robust memory response than anti-CTLA-4 alone, and increased survival in those models." (PMID 35326731, 2022). "Triggering of ICOS-L by OPN stimulates angiogenesis and tumor cell migration, whereas ICOS exerts a dominant negative effect on these activities." (PMID 36500861, 2022). "High co-overexpression of CTLA-4, PD-L1, and ICOS in normal lung (28 of 120 patients) was also significantly associated with decreased DFS (P = .0013), suggesting an immune tolerance to tumor neoantigens in some patients." (PMID 36108261, 2022). "LAYN+ Tregs showed highly expressed LAYN, TNFRSF9, and ICOS, but the proportion of this cell population in tumor‐infiltrating cells was very small, which was different from FOXP3+ Tregs." (PMID 35474948, 2022). "In this study, we show that among CD4+ TILs, the cells that coexpressed PD-1 and ICOS were enriched for tumor-reactive T cells in patients with HNSCC or CRC." (PMID 35439168, 2022). "The homogeneity of PD1 and ICOS on tumor cells and their maintained expression throughout passaging suggested a possible Tfh cell origin." (PMID 35510955, 2022). "In vivo, ICOS-Fc inhibits tumor growth and metastasis, development of osteoporosis, liver damage induced by acute inflammation following treatment with CCl4, and it favors skin wound healing." (PMID 36119089, 2022).
tumor (continued). "On the other side, ICOSL triggering mediated by ICOS exerts different functions via a reverse signal in other types of cells such as dendritic cells, endothelial cells, and tumor cells." (PMID 36405702, 2022). "In conclusion, we have shown that among the CD4+ Th TILs, cells coexpressing PD-1 and ICOS were enriched for tumor reactivity." (PMID 35439168, 2022). "ICOS was significantly upregulated on the surface of tumour-infiltrating CD8+ T cells compared with those in circulation in the treatment-naïve setting (p = 0.01)." (PMID 35366537, 2022). "The removal of ICOS-Fc from IL MIX resulted in it having a lesser effect on tumor growth (mass, volume), cell proliferation (Ki67), and immune modulation, in terms of IL-1β, IL-6, and IL-10 expression." (PMID 36500861, 2022). "Assessment of the tumor immune infiltrate showed that subcutaneous tumors of mice with liver metastases had reduced CD8+ T cell expression of activation markers including ICOS, PD-1 and CTLA-4, as well as expression of intracellular IFNγ." (PMID 36466910, 2022). "We found that AMPK-KO Tregs expressed higher levels of PD-1, Nrp1, and ICOS than Tregs from WT mice in both tumor-free and tumor-bearing mice." (PMID 34649584, 2021). "One of the essential mechanisms related to the ICOS/ICOSL pathway is the induction of anti-tumor response mechanisms such as stimulation of CD8+ T cell response." (PMID 34639059, 2021). "CD4+LAIR2+ cells highly expressed Treg cell lineage markers, including IL2RA, CTLA4, TNFRSF18, ICOS, TIGIT, and tumor-associated Treg cell marker CCR8, consistent with CD4+ LAIR2+ cells being of Treg lineage and not recently activated T cells." (PMID 35008369, 2021). "Next, we demonstrated that MSI-H CRC patients with increased IL2RB+ immune cells have an increased abundance of CD3, CD4 and FOXP3 TILs and higher PDL1 tumor and ICOS expression." (PMID 33928242, 2021). "In DCs, triggering of ICOSL with ICOS-Fc, a recombinant soluble form of ICOS, modulates cytokine secretion, promotes antigen cross-presentation, and inhibits adhesiveness and migration; in endothelial and tumor cells it inhibits adhesion and migration." (PMID 35052731, 2021). "Altogether, tumor growth inhibition after PD-1 blockade was due to the expansion of CD8+ T cells expressing the costimulatory molecule ICOS and a concomitant reduction in the frequency of CD4+Foxp3+ regulatory T cells." (PMID 34912335, 2021). "An interrogation of the expression pattern of the ligands to TIGIT and ICOS has shown distribution across different cellular compartments, which were significantly elevated in the tumour compared to the normal pancreas." (PMID 33917832, 2021). "Since the triggering of ICOSL by OPN, or alternatively by ICOS, exerts opposing effects on tumor cell migration, metastasis of B16-ICOSL-high and of B16-ICOSL-low cells in wild-type mice was compared, to assess the net effect of these opposing forces in vivo." (PMID 35052731, 2021). "On the other hand, serum butyrate levels limit the anti-tumor efficacy of anti-CTLA4 therapy in metastatic melanoma by restraining the up-regulation of CD80/CD86 on dendritic cells and ICOS on T cells, accumulation of tumor-specific T cells and memory T cells." (PMID 33708214, 2021). "In contradiction to this role, ICOS decreases anti-tumor immunity because of the increased function of Treg cells, mainly through the secretion of IL10 and TGF-β." (PMID 34639059, 2021). "Although this trial did not allow correlation with clinical outcome, it did show that CD4+ T cells from blood and tumor tissue of all treated patients increased the expression of ICOS and the production of IFN-γ." (PMID 33777008, 2021). "Subsequently, second-generation CARs containing an additional co-stimulatory signaling molecule, such as 4-1BB, CD28, CD27, OX40 or ICOS have been developed to stimulate an endogenous immune response against tumor cells via epitope spreading." (PMID 33442419, 2021).
tumor (continued). "Fresh cells tumor microenvironment analysis included phenotypic characterization of their T cell surfaces immune checkpoint markers PD-1, PD-L1, ICOS, TIM-3, LAG-3, 41-BB and BTLA." (PMID 34771650, 2021). "Especially, inhibitory molecules TIGIT, CTLA4, and co-stimulatory molecules ICOS, CD28 whose expression was higher in tumor-associated Treg cells compared to that from normal tissues, were highly expressed in decidual Tregs." (PMID 34168655, 2021). "Using the same 43rd percentile split established for IL2RB expression in the transcriptomics analysis, we observed a trend toward increased PDL1 tumor (P = 0.058) and ICOS expression (P = 0.1956) in the IL2RBHi patients." (PMID 33928242, 2021). "In future studies, the phenotypic and functional analyses of CD8 T cells expressing ICOS by mass cytometry will help to further define the role of ICOS+CD8 T cells for tumor immunity." (PMID 34912335, 2021). "The effect of ICOSL triggering by ICOS-Fc was evaluated in OPN-induced migration of several human tumor-cell lines expressing high (ICOSLhigh) or low (ICOSLlow) levels of ICOSL (respectively)." (PMID 33106594, 2020). "The frequency of ICOS+ cells was significantly increased (four-fold), specifically among CD8αβ T cells in the tumor tissue of Treg-depleted mice, compared to Treg-proficient mice." (PMID 32185408, 2020). "Of note is the correlation between CD3 and ICOS, both of which were independently prognostic within tumour compartments, highlighting the potential power of such multiplex discovery." (PMID 33261133, 2020). "Here, we show that Treg depletion affects tumor-infiltrating CD8αβ T cells alone and results in increased activation as measured by ICOS expression and expression of IFN-γ specifically in the tumors." (PMID 32185408, 2020). "ICOSL/ICOS are costimulatory molecules pertaining to immune checkpoints; their binding transduces signals having anti-tumor activity." (PMID 33106594, 2020). "This indicates that T cell subsets expressing the activation marker ICOS are less frequent in the bulk tumor as a proportion of marker-positive cells." (PMID 32763154, 2020). "To explore the potential for activation of the ICOS pathway to lead to anti-tumor immunity we generated ICOS antibodies." (PMID 32970735, 2020). "It has been reported that this therapeutic strategy enhances the density of tumor-infiltrating CD4+ T cells expressing the costimulatory molecule inducible T cell costimulator (ICOS)." (PMID 32194568, 2020). "The presence of ICOS+ lymphocytes and ICOS-L+ cells was found to have different prognostic value in various tumor settings." (PMID 32867025, 2020). "In mice, butyrate restrains anti-CTLA-4-induced up-regulation of CD80/CD86 on dendritic cells and ICOS on T cells, accumulation of tumor-specific T cells and memory T cells." (PMID 32358520, 2020). "Similar experiments were performed to investigate the role of ICOS in the anti-tumor response to either BI 853520 + anti-OX40 or BI 853520 + anti-4-1BB." (PMID 31959281, 2020). "We previously reported the increased numbers of total Tregs, ICOS+ Tregs and pDCs in peripheral blood of GC patients and Tregs, ICOS+ Tregs are accumulated in tumor tissue." (PMID 31777600, 2019). "High positive expression of PD-L1 and B7-H4 was observed in tumour cells (TCs), whereas PD-L1, B7-H3, B7-H4, IDO-1, VISTA, ICOS and OX40 were highly expressed in tumour-associated immune cells (TAICs)." (PMID 31722750, 2019). "In consideration of the role of ICOS, CD28 and CD80 genes in tumor immunity, we chose ICOS rs4404254 T>C, rs10932029 T>C, CD28 rs3116496 T>C and CD80 rs7628626 C>A SNPs to explore their potential roles in the etiology of HCC." (PMID 31235485, 2019). "Of note, whereas expression levels of HLA-DR and ICOS dropped again upon nodal tumor involvement, the expression levels of the immune checkpoints remained high or increased even further, indicative of a suppressed or “exhausted” state." (PMID 31118093, 2019).